KCNT1 (potassium sodium-activated channel subfamily T member 1)
Description:
Sodium-activated K(+) channel. Acts as an important mediator of neuronal membrane excitability. Contributes to the delayed outward currents (By similarity). Regulates neuronal bursting in sensory neurons (By similarity). Contributes to synaptic development and plasticity (By similarity).
Synonyms: KIAA1422; SLACK; Slo2.2; KCa4.1; DEE14; EIEE14; ENFL5; KNa1.1; bA100C15.2
Tractability: Small molecule: a structure with a bound ligand is known; a high-quality ligand is known; it belongs to a druggable protein family. Antibody: UniProt places it where antibodies can reach, with medium confidence; UniProt predicts a signal peptide or a membrane-spanning region; its Gene Ontology location is reachable by antibodies, with medium confidence; the Human Protein Atlas places it where antibodies can reach. PROTAC: a small molecule that binds it is known.
Gene: Protein-coding gene on chromosome 9 (135,702,185 to 135,795,508, forward strand). Ensembl gene ENSG00000107147.
Subcellular location: Cell membrane
Subcellular location (Human Protein Atlas): Plasma membrane; Nucleoplasm
Gene Ontology:
Molecular function: intracellular sodium-activated potassium channel activity; protein binding; outward rectifier potassium channel activity; chloride-activated potassium channel activity; potassium channel activity
Biological process: potassium ion transmembrane transport; protein homotetramerization; potassium ion transport; regulation of postsynaptic membrane potential
Cellular component: plasma membrane; membrane; postsynaptic density membrane
Genetic constraint (gnomAD): Loss-of-function variants: 77 observed, 136.42 expected, observed/expected ratio (o/e) 0.56, 90% interval 0.47 to 0.68. The synonymous counts are far from expectation, so gnomAD's model fits this gene poorly and the ratio says little. Missense variants: 1,417 observed, 1,650.7 expected, observed/expected ratio (o/e) 0.86, 90% interval 0.82 to 0.9. Synonymous variants: 867 observed, 706.91 expected, observed/expected ratio (o/e) 1.23, 90% interval 1.16 to 1.3.
Gene-disease validity (ClinGen):
ClinGen rates the evidence that KCNT1 causes each of these diseases.
childhood-onset epilepsy syndrome (autosomal dominant): Definitive. A epilepsy syndrome that occurs during childhood.
Homologues: Orthologues: chimpanzee KCNT1 (99% identical), macaque KCNT1 (99% identical), pig KCNT1 (94% identical), dog KCNT1 (89% identical), rat Kcnt1 (89% identical), mouse Kcnt1 (89% identical), guinea pig KCNT1 (86% identical), tropical clawed frog kcnt2l (83% identical), zebrafish kcnt1b (75% identical), zebrafish kcnt1a (69% identical), Drosophila melanogaster SLO2 (53% identical), Caenorhabditis elegans slo-2 (41% identical). Paralogues in human: KCNT2 (72% identical), KCNMA1 (20% identical), KCNU1 (18% identical).
Diseases named in the same sentence as KCNT1 in open-access papers:
KCNT1 is named in the same sentence as 68 diseases in open-access papers, as found by Europe PMC text mining. Sharing a sentence is not in itself a finding about the gene and the disease. The quoted sentences say what the papers report.
epilepsy (71 papers, 2014 to 2026). A brain disorder characterized by episodes of abnormally increased neuronal discharge resulting in transient episodes of sensory or motor neurological dysfunction, or psychic dysfunction. "In both cellular and Drosophila models, we have used several common mutations found in patients with KCNT1 epilepsy, involving different functional domains of the channel." (PMID 40944494, 2025). "KCNT1 mutations were present in approximately 50% of epilepsy of infancy with migrating focal seizures (EIMFS) cases, indicating that KCNT1 is a primary genetic cause of this disorder." (PMID 41189825, 2025). "In vitro studies have shown that KCNT1-epilepsy mutations are gain of function, significantly increasing K+ current amplitudes." (PMID 38336906, 2024). "Mutations in the KCNT1 potassium channel cause severe forms of epilepsy which are poorly controlled with current treatments." (PMID 38336906, 2024). "In summary, our study shows that the expression of patient-specific KCNT1 mutations in Drosophila gives a seizure phenotype, modelling human KCNT1-epilepsy." (PMID 38336906, 2024). "It has previously been shown in vitro to significantly reduce the K+ currents of WT42 and epilepsy-associated mutant KCNT1 channels." (PMID 38336906, 2024). "Quinidine has been used as an anticonvulsant to treat patients with KCNT1-related epilepsy by targeting gain-of-function KCNT1 pathogenic mutant variants." (PMID 38289338, 2024). "The prescribed antiarrhythmic drug, quinidine, has emerged as a precision therapy for KCNT1-related epilepsy by blocking Slack mutant variants in vitro and conferring decreased seizure frequency and improved psychomotor development in clinical treatment." (PMID 38289338, 2024). "KCNT1 mutations also cause other severe epilepsies beginning in infancy, including West Syndrome and Otahara Syndrome1." (PMID 38336906, 2024). "In 2018, a girl, Valeria, presented with a seizure shortly after birth and was diagnosed with epilepsy arising from a c.1421A>G mutation in KCNT1, which encodes for a sodium-activated potassium channel." (PMID 39062600, 2024). "Reducing KCNT1 expression through an ASO is a promising therapeutic strategy for epilepsy caused by gain-of-function KCNT1 mutations." (PMID 39595574, 2024). "KCNT1 mutations demonstrate a broad phenotypic spectrum among carriers and are often associated with severe epilepsy phenotypes, such as intellectual disability and mental and behavioral abnormalities." (PMID 38966089, 2024). "In vitro studies have shown that the ion channel blocker quinidine reduces the increased current amplitude produced by KCNT1-epilepsy mutations." (PMID 38336906, 2024). "Other variants of KCNT1 have been linked to other epilepsy-related conditions, including West and Ohtahara syndromes, which are rare forms of severe epilepsy in neonates." (PMID 38003469, 2023). "Disruption of KCNT1 (Potassium Sodium-Activated Channel Subfamily T Member1) gene expression causes epilepsy in infants with migratory focal seizures." (PMID 38069426, 2023). "Loss-of-function (LOF) mutations of the sodium channel gene SCN1A and GOF mutations of the potassium channel gene KCNT1 can also cause epilepsy." (PMID 37901435, 2023). "The p.(Gly288Ser) variant is one of the main recurrent variants in KCNT1-related disorder and is associated with its severe form; epilepsy of infancy with migrating focal seizures." (PMID 39669259, 2023). "The data presented here provide proof of concept for ASO-based gene silencing as a promising therapeutic approach in KCNT1-associated epilepsies." (PMID 36173683, 2022). "Considering that the KCNT1 T314A mutation challenges the accepted paradigm of the pathobiology underlying KCNT1-epilepsy, we have investigated its properties in more detail." (PMID 36499459, 2022).
epilepsy (continued). "Currently, QND is receiving attention for its use in epilepsy of infancy with migrating focal seizures (EIMFS) due to potassium sodium-activated channel subfamily T member 1 (KCNT1) genetic variants." (PMID 36297665, 2022). "KCNT1 mutations identified in patients with epilepsy were introduced into the full length human KCNT1 cDNA using quick-change site-directed mutagenesis protocol." (PMID 36499459, 2022). "KCNT1-related epilepsy can be associated with comorbidities including intellectual disability, autism, and behavioural features and can lead to premature death." (PMID 36499459, 2022). "Gain of function mutations of KCNT1 induce epilepsy, while loss of function of KCNT1 results in autism." (PMID 36066699, 2022). "In a case report on two pediatric patients affected by drug-resistant epilepsy caused by KCNT1 mutations and treated with QND, only one showed an 80% reduction in seizure frequency, while the second patient did not improve at all." (PMID 36297665, 2022). "Gain of function mutations in the KCNT1 gene are the cause of neurological disorders associated with different forms of epilepsy." (PMID 36499459, 2022). "Initial studies suggested that KCNT1-related epilepsy caused by a GOF variant responds to quinidine, a sodium and potassium channel blocker mostly used as an anti-arrhythmic." (PMID 35250833, 2022). "Many of the epilepsy causing mutations increase the sensitivity of KCNT1 channel to intracellular Na+, which explains large macroscopic K+ currents mediated by these mutant KCNT1 channels at the resting levels of Na+ concentration." (PMID 36499459, 2022). "To gain insights into the relation between the characteristics of the mutant KCNT1 channel with the severity of the epilepsy caused by the mutations in humans, we employed Spearman correlation analysis." (PMID 36499459, 2022). "A similar ASO strategy has been developed for GOF variants in KCNT1 that lead to epilepsy of infancy with migrating focal seizures (EIMFS)." (PMID 35250833, 2022). "This suggests that gain of function KCNT1 mutations cause epilepsy by increasing resting potassium conductance and suppressing the activity of inhibitory neurons." (PMID 36499459, 2022). "Fifteen years later, KCNT1 was identified as the major disease-causing gene of epilepsy of infancy with migrating focal seizures (EIMFS)." (PMID 36117860, 2022). "Functional studies have shown that KCNT1 pathogenic variants associated with epilepsy result in an overall gain-of-function effect on the channel activity, increasing the current up to 22-fold compared with the wild-type channel." (PMID 36173683, 2022). "To date, all but two reported KCNT1 mutations in epilepsy are heterozygous missense mutations, predicted to cause a single amino acid change in the KCNT1 potassium channel." (PMID 36499459, 2022). "Worldwide, more than 60 mutations of the KCNT1 have been found to be associated with various types of epilepsy." (PMID 36117860, 2022). "Human mutations of the Na+-activated K+ channel Slack (KCNT1) are associated with epilepsy and intellectual disability." (PMID 34664085, 2021). "The large fast AHP is reminiscent of that caused by a mutation in KCNT1 associated with epilepsy, which causes neurons to be hyperexcitable due to increased potassium currents and an increased AHP amplitude." (PMID 34535765, 2021). "Another set of mice were generated with the Kcnt1 R455H missense mutation, which was chosen because this produced the largest gain of function seen in an analysis of multiple epilepsy-associated mutations." (PMID 32081855, 2020). "The mouse R455H Kcnt1 mutation corresponds to the human mutation, KCNT1 R474H, which causes very early onset epilepsy, together with very severe intellectual disability." (PMID 32081855, 2020). "Pathogenic variants in KCNT1 cause a wide spectrum of severe epilepsies typically associated with impaired neurologic development and significant disease burden." (PMID 29196579, 2018).
epilepsy (continued). "Out of the 14 patients carrying 22q13 deletions and having seizures, 4 were carrying an additional CNV covering a known risk gene for epilepsy: KCNT1 (OMIM: 608167), MYT1L (OMIM: 613084), DEAF1 (OMIM: 602635) and SLC25A22 (OMIM: 609302)." (PMID 29263841, 2017). "Additionally, we address the topic of epilepsy resulting from mutations in the KCNT1 gene and the therapeutic strategies currently available for managing these challenging conditions." (PMID 41765992, 2026). "Progress in these areas could ultimately open new avenues for treating KCNT1-related epilepsies and other neurological disorders linked to neuronal hyperexcitability." (PMID 41189825, 2025). "KCNT1 mutations can cause a range of epilepsy and neurodevelopmental disorders." (PMID 38966089, 2024). "Reducing the activity of inhibitory neurons may explain how neuronal hyperexcitability, the mechanism underlying seizures, occurs in KCNT1-epilepsy." (PMID 38336906, 2024). "Thus, successful modelling of human KCNT1-epilepsy with these mutations would be relevant for a significant proportion of patients." (PMID 38336906, 2024). "Over 50 mutations in KCNT1 (Slack) have been identified and related to seizure disorders." (PMID 38289338, 2024). "Reports of beneficial effects of quinidine in patients with KCNT1 mutations are increasing dramatically, supporting the use of quinidine in the treatment of epilepsy of infancy with migrating focal seizures (EIMFS), which is also known as migrating partial seizures of infancy (MPSI)." (PMID 37630977, 2023). "Mutations of KCNT1 lead to severe early-onset epilepsy, usually accompanied by other comorbidities." (PMID 36117860, 2022). "The epilepsy phenotypes associated with each of the KCNT1 mutations could be expanded in the future, as informed by further genetics studies, which may alter the scoring of the mutation phenotypes." (PMID 36499459, 2022). "However, there is evidence that epilepsy-causing mutations increase positive cooperativity of the KCNT1 channel opening, which can also explain the increase of the macroscopic current amplitude." (PMID 36499459, 2022). "As expected, epilepsy-causing mutations significantly increased the amplitude of KCNT1 currents." (PMID 36499459, 2022). "Furthermore, KCNT1 is a causative gene in infants with hypomyelinating leukodystrophy showing WM alterations, and KCNT1 mutations occur in infant epilepsy associated with delayed myelination, thin corpus callosum, and WM hyper-intensity in MRI." (PMID 34276310, 2021). "Interestingly, KCNT1 gain-of-function mutations also give rise to other epilepsies including ANDFLE15,16, which has an onset later in childhood, typically at ~8–10 years." (PMID 32081855, 2020). "Currently the therapeutic effects of quinidine in KCNT1-related epilepsy remain largely unknown and more work is required, although it seems a promising treatment option due to gain-of-function mutations in KCNT1." (PMID 28082152, 2018). "Our results suggested that the preference transition in thermotaxis might be useful as a model system for early-onset epilepsy caused by Slack/KCNT1 mutations." (PMID 30272003, 2018). "The normal role of the KCNT1 channel is to reduce neuronal excitability and so it appears paradoxical that mutations leading to overactivity of the channel could contribute to neuronal hyperexcitability in epilepsy." (PMID 40944494, 2025). "Together, the three KCNT1 mutations investigated in this study account for approximately one fifth of patients identified to date, thus dosing information and any candidate drugs identified using the models will potentially benefit a significant proportion of people with KCNT1 epilepsy." (PMID 38336906, 2024).
epilepsy (continued). "To analyze the effects of the 4 prioritized drugs on KCNT1‐related seizures in vivo, we used our humanized Drosophila models of KCNT1 epilepsy." (PMID 40944494, 2025). "Although they are yet to reach clinical use, the efficacy of KCNT1 inhibitors in suppressing electrical activity in mouse models of epilepsy is particularly encouraging." (PMID 40944494, 2025). "Nonselective cation channel blocking drugs, such as quinidine and bepridil, have been shown to inhibit KCNT1 channels in in vitro experiments, with quinidine having been trialed as a stratified treatment for KCNT1 epilepsy." (PMID 40944494, 2025). "KCNT1‐related disorders include epilepsy of infancy with migrating focal seizures and sleep‐related hypermotor epilepsy." (PMID 40944494, 2025). "Based on these findings, we consider antrafenine as the lead candidate new drug for KCNT1 epilepsy from this study." (PMID 40944494, 2025). "The action of the 4 drugs was then analyzed in vivo and 2 were found to reduce the seizure phenotype in humanized Drosophila KCNT1 epilepsy models." (PMID 40944494, 2025). "Seizure reduction efficacy in rodent models of KCNT1 epilepsy will be required to justify its future clinical evaluation in patients with KCNT1 epilepsy." (PMID 40944494, 2025). "The 2 potential new drugs for treating people with KCNT1 epilepsy, antrafenine and nelfinavir mesylate, are yet to be trialed in patients for this indication." (PMID 40944494, 2025). "Its clinical use for the treatment of KCNT1-related epilepsies was initially investigated by in vitro experiments and clinically challenged later." (PMID 38931004, 2024). "KCNT1-related epilepsy patients suffer not only with frequent, early-onset seizures, but also with cognitive impairments, movement disorders, and sometimes additional behavioral and/or psychiatric problems." (PMID 39392867, 2024). "To investigate if Drosophila can be used to model human KCNT1 epilepsy, we generated Drosophila melanogaster lines carrying human KCNT1 with the patient mutation G288S, R398Q or R928C." (PMID 38336906, 2024). "Several small-molecule inhibitors against Slack have been reported, providing informative starting points for drug development efforts with KCNT1-related epilepsy." (PMID 38289338, 2024). "Another repurposed antiarrhythmic drug, clofilium, has been proposed as a therapeutic tool for KCNT1-related epilepsies, besides being devoid of clinical significance." (PMID 38931004, 2024). "Despite that initial results were quite encouraging, the extensive use of quinidine in KCNT1-related epilepsies was strongly questioned when larger and systematic clinical studies were performed." (PMID 38931004, 2024). "These insights about a Slack-NaV1.6 complex challenge the traditional view of ‘Slack as an isolated target’ for anti-epileptic drug discovery efforts and can guide the development of innovative therapeutic strategies for KCNT1-related epilepsy." (PMID 38289338, 2024). "It is plausible that the Slack-NaV1.6 interaction contributes to the therapeutical role of quinidine in the treatment of KCNT1-related epilepsy." (PMID 38289338, 2024). "We chose three Slack pathogenic mutant variants (K629N, R950Q, and K985N) initially detected in patients with KCNT1-related epilepsy." (PMID 38289338, 2024). "Our study shows that Drosophila has the potential to model human KCNT1- epilepsy and can be used as a tool to assess new treatments for KCNT1- epilepsy." (PMID 38336906, 2024). "Given that many patients are refractory or nonresponsive to conventional anticonvulsants, and considering the limited success of quinidine in clinical treatment of KCNT1-related epilepsy, inhibitors targeting Slack are needed urgently." (PMID 38289338, 2024).